RICTOR (RPTOR independent companion of MTOR complex 2)
Diseases named in the same sentence as RICTOR in open-access papers (continued):
Sharing a sentence is not in itself a finding about the gene and the disease.
colorectal cancer (6 papers, 2018 to 2025). A primary or metastatic malignant neoplasm that affects the colon or rectum. "Another study reported that the loss of expression of SMAD4-induced RICTOR/AKT signaling activation was correlated with the poor survival of patients with colorectal carcinoma." (PMID 36142267, 2022). "Similarly, the expression of autophagy-related genes like BECLIN1, RAPTOR and RICTOR is associated with the development and progression of colorectal carcinoma (CRC) as well as the emergence of multidrug resistance." (PMID 38994937, 2024). "Many studies have demonstrated that patients with a high expression of RICTOR in tumor tissue samples have a lower overall survival in cancers, such as small cell lung cancer, colorectal cancer and esophageal squamous cell carcinoma." (PMID 32041519, 2020). "Another study reported that the positive expression rate of RICTOR in colorectal cancer tissues was 58.1% (36/62), which correlated with Dukes stage, lymphatic metastasis and prognosis." (PMID 32041519, 2020). "More specifically, increased expression of RICTOR is associated with tumor progression and poor survival in CRC, and mTOR activity and complex distribution are independent prognostic factors in colorectal carcinoma." (PMID 29455662, 2018).
lung adenocarcinoma (6 papers, 2017 to 2026). A carcinoma that arises from the lung and is characterized by the presence of malignant glandular epithelial cells. "In addition, Dennis (2018) found that RICTOR mutations were present in early and advanced lung adenocarcinomas, and the amplification of RICTOR predicted poor overall survival in advanced LUAD patients (OS, HR: 1.73, 95% CI: 1.23–2.42, p = 0.0015)." (PMID 32041519, 2020). "However, the prognostic impact of RICTOR mutations in epidermal growth factor receptor (EGFR)-mutant lung adenocarcinoma remains unclear." (PMID 42080921, 2026). "Using genomic and expression data from advanced non-small cell lung cancer (NSCLC) patients enrolled in the BATTLE-2 clinical trial, we identified RICTOR alterations in a subset of lung adenocarcinomas and found RICTOR expression to carry worse overall survival." (PMID 30338041, 2018). "Overexpression of Rictor frequently occurs in human cancers, and RICTOR amplification has been identified in breast cancer, residual triple negative breast cancers following neoadjuvant therapy and lung adenocarcinomas with mTORC1/2-inhibitor susceptibility." (PMID 28082369, 2017). "In 2015, Cheng evaluated an 18-year-old male never-smoker with lung adenocarcinoma for possible targeted therapy and found that the amplification of RICTOR was the only operable genomic alteration." (PMID 32041519, 2020).
non-small cell lung carcinoma (6 papers, 2018 to 2023). A group of at least three distinct histological types of lung cancer, including non-small cell squamous cell carcinoma, adenocarcinoma, and large cell carcinoma. "The alteration frequency of RICTOR mutations was highest in Non-Small Cell Lung Cancer (LUAD and LUSC), with a frequency of approximately 12%." (PMID 37372460, 2023). "Rapamycin-insensitive companion of mTOR (RICTOR) amplification promotes non-small cell lung cancer proliferation via generation of mTORC2." (PMID 35859795, 2022). "RICTOR, a component of mTORC2, was found to be amplified in beast cancer, non-small cell lung cancer (NSCLC), and particularly in squamous cell lung carcinoma (SQCLC), in which RICTOR amplification is significantly related to poor prognosis and short survival." (PMID 30754640, 2019). "This review describes the mechanisms of targeted-drug resistance and newly identified non-small cell lung cancer targets (e.g., KRAS G12C, NGRs, DDRs, CLIP1-LTK, PELP1, STK11/LKB1, NFE2L2/KEAP1, RICTOR, PTEN, RASGRF1, LINE-1, and SphK1)." (PMID 36909198, 2023).
colon carcinoma (5 papers, 2017 to 2025). "Furthermore, downregulation of miR-424/503 is associated with RICTOR upregulation in colon cancer tissues." (PMID 29455662, 2018). "RICTOR is upregulated via the repression of the miR-424/503 cluster in colon cancer cell lines that harbor c-SRC upregulation." (PMID 29455662, 2018). "Impairment of tumor growth by RICTOR blockade in vivo has been described for other cancer entities such as colon cancer and malignant pheochromocytoma." (PMID 28445935, 2017). "Furthermore, the depletion of SMAD4 expression or the activation of RICTOR/AKT signaling contributed to resistance to irinotecan in colon cancer cells." (PMID 36142267, 2022). "To confirm if RICTOR-mediated UGCG regulation exists in other cell types, we silenced RICTOR in HCT-116 (human colon cancer cells) and HEK-293 (human embryonic kidney) cells and observed a decrease in glucosylceramides." (PMID 40934285, 2025).
glioblastoma (5 papers, 2017 to 2024). The most malignant astrocytic tumor (WHO grade IV). "We found that Lpd and EGFR mutually co-operate and Lpd interacts with the rapamycin-insensitive companion of mTOR (RICTOR) consequently critically co-regulating glioblastoma invasion and radiation sensitivity." (PMID 34771501, 2021). "Among the five overlapping interacting partners was RICTOR, which caught our attention due to its molecular connection to the majority of Lpd associated functions, EGFR-related signaling, and glioblastoma radioresistance." (PMID 34771501, 2021). "Yet, the commonality of EGFR in radiosensitivity induced by knockdown of Lpd and RICTOR indicates that the Lpd-RICTOR-EGFR signaling pathway is a fundamental mechanism in glioblastoma." (PMID 34771501, 2021). "Mechanistically, EGFR signaling together with an interaction between Lpd and the Rapamycin-insensitive companion of mammalian target of rapamycin (RICTOR) jointly regulate glioblastoma radiosensitivity." (PMID 34771501, 2021). "In glioblastoma multiforme, the acetyl-CoA-dependent acetylation of RICTOR, a core component of the mTORC2 signaling complex, promotes an autoactivation loop, even when the upstream growth factor driving this signaling pathway is removed." (PMID 34130715, 2021). "Taken together, our data suggest a hitherto undescribed Lpd-RICTOR interaction and an involvement of both proteins in glioblastoma cell radiosensitivity." (PMID 34771501, 2021). "In addition, our study discovered a novel interaction of Lpd with RICTOR, a regulator of glioblastoma radiosensitivity and chemoresistance in tumors with mutated EGFR by facilitating NFκB signaling." (PMID 34771501, 2021). "At the molecular level, we discovered a so-far-unknown protein complex consisting of Lamellipodin and RICTOR and that Lamellipodin mediates glioblastoma radiation survival via EGFR signaling." (PMID 34771501, 2021). "Indeed, RICTOR has been shown to impair c-Myc expression in glioblastoma cells and c-Myc is known to interact with HIF-1α in cancer cells." (PMID 28445935, 2017). "Finally, involvement of mTORC2/RICTOR in cancer metabolism and therapy resistance has been shown in glioblastoma." (PMID 28445935, 2017). "Consequently, Lpd and RICTOR may interconnect with the Ena/VASP or Scar/WAVE complex to facilitate invasion in glioblastoma." (PMID 34771501, 2021). "JR-AB2-011 was shown to disrupt mTOR binding to RICTOR and suppress AKT phosphorylation in glioblastoma cells after 24 h of treatment." (PMID 39259491, 2024). "Taken together, these data indicate a novel regulatory network between Lpd, RICTOR and EGFR in glioblastoma that jointly determines cell fate upon X-ray irradiation." (PMID 34771501, 2021). "Thus, our results suggest that Lpd, RICTOR and EGFR lie within the same signaling axis for the regulation of glioblastoma cell radiosensitivity." (PMID 34771501, 2021).
metastatic tumors (4 papers, 2018 to 2024). "A recent study analyzing matched primary and metastatic lung cancer pairs has revealed that RICTOR amplification is associated with metastatic tumors, implying the potential of this genetic alteration to drive the metastatic process." (PMID 34958428, 2021). "The metastatic tumors retained most of the genetic variants found in the original tumors, but some cases had additional CNVs, including copy number gains for the KRAS, AKT3, RICTOR, FGFR, and FANCD2 genes, and copy number losses for the MYC and RAD50 genes." (PMID 34422662, 2021). "We found that high RICTOR mRNA levels in metastatic tumors (367 out of 448 total samples) positively correlate with patients’ survival, as indicated by a Kaplan-Meier curve obtained from patients falling in the first (n = 87) and fourth (n = 91) quartile of RICTOR expression." (PMID 38755661, 2024).
small cell lung carcinoma (4 papers, 2017 to 2023). Small cell lung cancer (SCLC) is a highly aggressive malignant neoplasm, accounting for 10-15% of lung cancer cases, characterized byrapid growth, and early metastasis. "These underline the significance of validated RICTOR amplification targets in small cell lung cancers or other malignancies." (PMID 37949943, 2023). "Nevertheless, patients with RICTOR amplification in gastric and small cell lung cancer were sensible to treatment with mTOR kinase inhibitors and were subsequently identified as a subgroup that responded to the treatment." (PMID 35096817, 2021). "Additionally, RICTOR has been identified as the most frequently amplified gene in a cohort of metastatic, small, cell lung cancer (SCLC) patients (~14% of patients) and SCLC patients, with RICTOR amplification having a significantly decreased overall survival." (PMID 37372460, 2023).
breast tumors (3 papers, 2025). "In contrast, mTORC1 effectors P-EIF4EBP1 and P-RPS6 exhibited diminished phosphorylation in RICTOR-altered breast tumors." (PMID 40019775, 2025). "To validate any deregulation of RICTOR expression in luminal breast tumors, we evaluated the RICTOR expression by immunoblotting in tumor and adjoining matched normal breast tissues from luminal cancer patients." (PMID 40934285, 2025).
cervical cancer (3 papers, 2022 to 2023). A primary or metastatic malignant neoplasm involving the cervix. "To confirm the function of RICTOR in tumor growth, we selected cervical cancer cell line, Hela, to examine the effect of RICTOR knockdown on cell growth." (PMID 37372460, 2023). "Our results are also consistent with those of a previous study in which miR-155 transfection in human nasopharyngeal cancer and human cervical cancer cells inhibited several components of PI3K-Akt-mTOR signaling, including RHEB, RICTOR, phosphorylated mTOR and Akt." (PMID 36076283, 2022).
Insulin resistance (3 papers, 2014 to 2023). Increased resistance towards insulin, that is, diminished effectiveness of insulin in reducing blood glucose levels. "RICTOR avoids toxicity in neurons caused by Aβ formation and is also involved in formation of Aβ induced by insulin resistance." (PMID 37155564, 2023). "Fat-specific RICTOR deletion leads to insulin resistance as the mice display elevated levels of circulating insulin but reduced insulin sensitivity at young age." (PMID 36812323, 2023). "While our results do not exclude that insulin resistance is a driver of the metabolic dysfunction in RICTOR mutant animals, they show that, in mice, insulin resistance is not necessarily coupled with a short life." (PMID 36812323, 2023).
invasive breast carcinoma (3 papers, 2021 to 2025). A carcinoma that infiltrates the breast parenchyma. "RICTOR being a key component of mTORC2, earlier studies on the analysis of The Cancer Genome Atlas (TCGA) curated invasive breast carcinoma patient datasets showed a significant correlation of RICTOR upregulation, mutation, or amplification with low overall survival." (PMID 40934285, 2025). "RICTOR alterations (gene amplification/mRNA overexpression) also correlated with decreased overall patient survival in invasive breast carcinoma datasets." (PMID 40019775, 2025).
myxofibrosarcoma (3 papers, 2020 to 2024). A malignant fibroblastic neoplasm arising from the soft tissue. "This study provides evidence that integrin α10 subunit may control growth and metastasis development in myxofibrosarcoma, and targeting integrin α10/TRIO/RICTOR pathway with EHop-016 and INK128 inhibitors could be clinically beneficial for myxofibrosarcoma patients." (PMID 34957097, 2021). "A study analyzed the gene expression profile of 64 cases of primary myxofibrosarcoma and found that patients with high ITGA10 expression had a significantly worse prognosis, revealing that ITGA10 promotes tumor cell survival by activating TRIO/RICTOR signaling." (PMID 33335550, 2020).
oral cancer (3 papers, 2012 to 2015). "Uesugi demonstrated that loss of miR-218 activated mTOR-Akt signaling pathway through direct targeting RICTOR in oral cancer." (PMID 26610476, 2015). "Their findings that forced miRNA-218 expression in oral cancer cell lines, lacking endogenous miRNA-218, can induce caspase-mediated apoptosis in these cells, highlights the relevance of RICTOR-regulated AKT activity to apoptosis protection." (PMID 22384145, 2012).
ovarian carcinoma (3 papers, 2016 to 2023). A malignant neoplasm originating from the surface ovarian epithelium. "RICTOR, a mTORC2 complex member, is also identified as upregulated, and reported as associated with cisplatin resistance through the inhibition of AKT degradation in ovarian cancer cells, and respective downregulation sensitized cells to cisplatin." (PMID 27090655, 2016). "The constitutive activation in ovarian cancer is a result of amplification of pathway components like PI3K subunits (p110), AKT isoforms (AKT1, AKT2, or AKT3), or members of the mTOR complexes (RICTOR, RAPTOR)." (PMID 27090655, 2016). "Contrary to other ovarian cancer cell lines, protein expression of the mTORC2 complex components, mTOR and RICTOR, displayed a modest increase rather than a decrease during mitotic arrest when compared to interphase cells." (PMID 28152500, 2017).
pancreatic cancer (3 papers, 2017 to 2018). "Knockdown of RICTOR by RNA interference in human pancreatic cancer cell lines has an inhibitory effect on tumor growth in vitro and in vivo." (PMID 29455662, 2018). "The knockdown of RICTOR in two primary PanIN (pancreatic tumor precursor) cell lines established from mice with early PanIN, reduced proliferation in both cell lines and enhanced the expression of senescence-associated beta galactosidase." (PMID 29455662, 2018). "In conclusion, results from our experiments demonstrate that RICTOR inhibition impairs tumor growth from pancreatic cancer cell lines at least in part via effects on proliferation and vascularization." (PMID 28445935, 2017). "Next, we assessed the effects of RICTOR knock-down on growth of pancreatic cancer cell lines in vitro." (PMID 28445935, 2017). "RICTOR inhibition showed impairment of AGC kinase activation including AKTSer473 in pancreatic cancer cell lines." (PMID 28445935, 2017). "In conclusion, RICTOR knock-down leads to modest, but still significant reduction of growth in pancreatic cancer cell lines." (PMID 28445935, 2017). "From these results we conclude that targeting RICTOR has growth inhibitory effects on pancreatic cancer cells in vivo." (PMID 28445935, 2017). "Here, we sought to analyze the effects of RICTOR inhibition in human pancreatic cancer cell lines in vitro and in vivo." (PMID 28445935, 2017). "Pursuant to the modulation of hypoxia-induced HIF-1α expression, VEGF-A secretion from pancreatic cancer cell lines was significantly reduced upon RICTOR inhibition after incubation with DFX." (PMID 28445935, 2017). "Taken together, RICTOR blockade impairs constitutive phosphorylation of AGC kinases in pancreatic cancer cells." (PMID 28445935, 2017). "In the present study we assessed the role of mTORC2/RICTOR in pancreatic cancer cell lines and human tissue samples." (PMID 28445935, 2017). "RICTOR/mTORC2 are increasingly recognized as important players in pancreatic cancer development." (PMID 29455662, 2018). "Hence, targeting the mTORC2 component RICTOR decreases hypoxia-driven HIF-1α expression in pancreatic cancer cell lines and potentially affects factors that are influenced by this transcription factor." (PMID 28445935, 2017). "Indeed, we and others have shown that treatment of pancreatic cancer cells with the mTORC1 inhibitor rapamycin induces AKTSer473 phosphorylation which can be abrogated by simultaneous RICTOR inhibition." (PMID 28445935, 2017). "Moreover, we determined the expression of RICTOR in 85 samples from patients that underwent surgery for pancreatic cancer by immunohistochemistry." (PMID 28445935, 2017). "With regard to PDAC, other signaling pathways such as Kras/Mek/Erk or src may also play a critical role in the proliferation and growth of pancreatic cancer cells, providing a partial explanation for the modest effects of RICTOR inhibition." (PMID 28445935, 2017). "In summary, RICTOR inhibition impairs secretion of hypoxia-induced VEGF-A secretion and constitutive IL-8 secretion from pancreatic cancer cell lines which potentially affects the surrounding tumor stroma." (PMID 28445935, 2017).
acute kidney injury (2 papers, 2024). Sudden and sustained deterioration of the kidney function characterized by decreased glomerular filtration rate, increased serum creatinine or oliguria. "For instance, the expression level RICTOR is significantly associated with a decreased risk of CKD and an increased level of eGFRcys, corroborating previous studies that highlighted its crucial role in protecting against kidney diseases, including acute kidney injury and renal inflammation." (PMID 38892221, 2024).
astrocytoma (2 papers, 2018). "More recently, AKT expression and phosphorylation and RICTOR and Ki-67 expression have been evaluated in 195 human astrocytomas of different malignancy degree and 30 healthy controls." (PMID 29692710, 2018). "This analysis revealed that AKT expression and phosphorylation increases with the histological grade and correlates with a worse overall survival in GBMs, while RICTOR is overexpressed in grade I and II astrocytomas and a shift to a nuclear localization has been demonstrated in GBMs." (PMID 29692710, 2018).
bladder cancer (2 papers, 2020 to 2022). "RICTOR, a cis-effect gene assigned to 5p at the protein level, is a critical regulator of cell migration and invasion in bladder cancer cell lines." (PMID 35659036, 2022). "Therefore, selectively targeting RICTOR can be a novel strategy for patients with invasive bladder cancer." (PMID 32041519, 2020). "Knockdown of RICTOR could inhibit the migration and invasion of bladder cancer cells by decreasing the levels of Rac1-GTP and phospho-paxillin." (PMID 32041519, 2020).
carcinoids (2 papers, 2017). "There were fewer CNAs in carcinoids than in carcinomas; however ACs showed a hybrid pattern, whereby gains of TERT, SDHA, RICTOR, PIK3CA, MYCL and SRC were found at rates similar to those in carcinomas, whereas the MEN1 loss rate mirrored that of TCs." (PMID 27873319, 2017).
diabetes (2 papers, 2024). "We translated their relevance to humans using UK Biobank data and showed that variants in RICTOR and GFM1 are associated with an elevated risk of age-related heart disease, dementia, diabetes, kidney, and liver diseases." (PMID 38293129, 2024).